NRAS (NRAS proto-oncogene, GTPase)
Diseases named in the same sentence as NRAS in open-access papers (continued):
Sharing a sentence is not in itself a finding about the gene and the disease.
nevus (18 papers, 2013 to 2026). Nevus (or naevus, plural nevi or naevi, from nævus, Latin for "birthmark") is the medical term for sharply circumscribed[1] and chronic lesions of the skin or mucosa. "Studying nevus formation as a phenotypic trait led to the identification of Cdon, a regulator of sonic hedgehog, as a key gene impacting nevi development in the context of an NRAS mutation." (PMID 38694815, 2024). "There is a 2-step pathogenesis of melanocytomas: the initiating genetic abnormality, usually BRAF/NRAS, leading to the development of a nevus, and the subset-defining genetic abnormality leading to a melanocytoma." (PMID 40123790, 2025). "This type of nevus is usually caused by an activating mutation in the MAPK pathway, mainly the NRAS gene." (PMID 36834954, 2023). "Focused amplicon deep sequencing on DNA extracted from the brain tumor and a cutaneous nevus revealed a heterozygous (c.37G > C; p.G13R) substitution in the NRAS gene." (PMID 25330907, 2014). "Last but not least, considering the fact that mosaic NRAS and BRAF pathogenic variants are abundant in CMN, the researchers generally agree that they initiate congenital nevus development, but they do not trigger malignancy on their own." (PMID 34643354, 2021).
skin cancer (18 papers, 2013 to 2025). "The V600E mutation site of the BRAF gene and the Q61R mutation site of the NRAS gene were highly prevalent in ectoderm-derived skin cancer and endoderm-derived thyroid tumors." (PMID 33308219, 2020). "In skin cancer, Pi was an essential nutrient for cell proliferation and for the promotion of tumorigenesis via the activation of the neuroblastoma RAS viral oncogene homolog (NRas)." (PMID 32461965, 2020). "With this respect, all patients of our cohort with oncogenic alterations within the MAPK pathway (KRAS and NRAS) presented skin tumors at any time point during disease course, and the NRAS-mutated patient progressed from extensive tumor stage to systemic dissemination." (PMID 34771672, 2021). "Interestingly, Malin reported two cases of PIMM in children, both with oncogenic mutations of NRAS in the tumor; skin dysplasia manifested as congenital skin nevus without a skin tumor, and melanocytes in the pial meninges progressed to aggressive PIMM." (PMID 39650061, 2024). "Similarly to recurrent BRAF mutations, non-canonical C>T, C>A, T>A, and T>C mutations in NRAS are 2.6- to 38-fold enriched within skin cancers compared with non-skin cancers." (PMID 33207206, 2020).
thyroid nodule (17 papers, 2014 to 2026). A small circumscribed mass in the THYROID GLAND that can be of neoplastic growth or non-neoplastic abnormality. "In indeterminate thyroid nodules, NRAS mutations are typically the most frequent, followed by KRAS and HRAS." (PMID 40748901, 2025). "In one unique case of a female, different multiple mutations were found in her three thyroid nodules: CCDC6/RET + NRAS Q61R in the first nodule, CCDC6/RET + KRAS G13D in the second nodule, and NRAS Q61R + PTEN Q245* in the third nodule." (PMID 37882481, 2023). "In conclusion, determining NRAS mutation status in FNs is expected to further improve the accuracy of cancer diagnoses and also to help predict cancer risk in thyroid nodules accompanying FNs." (PMID 25254041, 2014). "In a study that demonstrated the variety in the molecular profile of 96 surgically resected thyroid nodules, RAS (HRAS, NRAS, KRAS) oncogene mutations were present, either alone or with other mutations in almost one-half of cases (46 of 96 cases; 48%)." (PMID 37175943, 2023). "Thyroid nodules with CNAs alone or in conjunction with lower risk mutations such as HRAS, NRAS, DICER1, EIF1AX, and GEA are more likely to be low-risk neoplasms." (PMID 36551633, 2022). "This study aimed to investigate the diagnostic utility of BRAF, NRAS, and TERT promoter mutation in thyroid nodules at Dharmais Cancer Hospital." (PMID 33247684, 2020). "Mutations in RAS proto-oncogenes (NRAS, HRAS, KRAS) are common in thyroid nodules, though their prognostic significance remains unclear." (PMID 41784850, 2026). "The RAS genes family (NRAS, HRAS, and KRAS) mutations represent the majority (about 70%) of all mutated cases, especially in indeterminate cytology, and they can be seen in histologically benign and malignant thyroid nodules." (PMID 38884926, 2024). "Of note, Bethesda category V and VI thyroid nodules have a strong correlation with BRAF V600E mutations, whereas intermediate thyroid nodules categorized as Bethesda III and IV are associated with H, K, or NRAS or EIF1AX mutations, CNAs, or GEP." (PMID 39766147, 2024). "Therefore, several molecular tests for adjustment of cytological diagnosis of thyroid nodules have been proposed, which included panel of somatic mutations (e.g., BRAF and NRAS mutation and/or RET/PTC translocation) and immunocytochemistry tests based on gene expression signatures." (PMID 25972898, 2015). "Furthermore, molecular analysis using the following markers (BRAF V600E, NRAS, HRAS, KRAS, RET/PTC, and PAX8/PPARg) to evaluate preoperative genetic mutations and rearrangements has been shown to have significant diagnostic value in thyroid nodules with indeterminate cytology." (PMID 37732121, 2023). "In thyroid nodules with no aggressive features, GEA was most commonly associated with the HRAS mutation (n = 12, 34.3%), NRAS mutation (n = 10, 28.6%), and CNA (n = 8, 22.8%)." (PMID 36612045, 2022).
thyroid tumor (17 papers, 2012 to 2026). A benign or malignant neoplasm affecting the thyroid gland. "Our work showed promise in identifying characteristic protein patterns associated with specific thyroid tumors, including NIFTPs, also considering their NRAS mutational status." (PMID 40790099, 2025). "In one such study, 52% of thyroid tumor specimens carried clinically relevant mutations in at least one screened gene, most frequently involving KRAS (86%), followed by NRAS (7%), BRAF (6%), and combined NRAS + BRAF mutations (2%)." (PMID 41595518, 2026). "Human thyroid tumors are often characterized by activating point mutations in BRAF, NRAS, HRAS, or KRAS, leading to the overactivation of MAPK- and mTOR-signaling pathways." (PMID 40711277, 2025). "In this study, we introduce subcellular localization, an erstwhile unconsidered factor, as a determinant of the dissemination potential of thyroid tumors driven by either HRAS or NRAS oncoproteins." (PMID 32927904, 2020). "Overall, contrarily to the prevailing concept that bigger tumors are more prone to metastasize, we herein demonstrate that HRAS/NRAS-driven thyroid tumors exhibit the opposite behavior." (PMID 32927904, 2020). "In line with this, the NRAS codon 61 point mutations were only observed in FTC specimen in three cases (21.4%), which was the second most frequently mutated gene among the thyroid tumor samples." (PMID 32333269, 2020). "Among the 11 thyroid tumor samples, BRAF (5/11, 45.5%) was the gene most frequently mutated, followed by NRAS (3/11, 27.3%)." (PMID 32333269, 2020). "In contrast, in human medicine, the molecular characterization of thyroid tumor-ascertained mutations in BRAF, NRAS, HRAS, and KRAS is relevant as they are players implicated in thyroid tumor progression through their activation of MAPK- and mTOR-signaling pathways." (PMID 40711277, 2025). "There are 3 isoforms of RAS: HRAS, KRAS and NRAS found in thyroid tumours." (PMID 27703585, 2016). "In a series of 96 thyroid tumours whose mutational profiles of BRAF, IDH1 and NRAS mutations and RET/PTC were previously determined, we investigated MLH1 and MGMT expression and methylation status by qPCR and methylation-specific PCR after bisulphite treatment, respectively." (PMID 23414134, 2013). "On the other hand, Furin is significantly more expressed in thyroid neoplasms when compared to the normal tissue, and its high expression was correlated with the malignant histotype and clinicopathological parameters such as male sex, lymph node metastasis, and NRAS wild-type status." (PMID 37568724, 2023). "The pituitary tumor samples revealed no mutations, while among the thyroid tumor samples BRAF (6/14, 42.9%) was the most frequently mutated gene, followed by NRAS (3/11, 27.3%)." (PMID 32333269, 2020).
lymph node metastasis (16 papers, 2014 to 2025). "All patients with NRAS mutation had lymph node metastasis, proving that this mutation has an important role in more aggressive tumor behavior." (PMID 34110110, 2022). "The association of NRAS mutation was analyzed with the following: age, gender, location, lymph node metastasis, ulceration, mitotic index, tumor‐infiltrating lymphocytes (TILs), necrosis, tumor thickness, lymphovascular invasion (LVI), and tumor size." (PMID 34110110, 2022). "From the same patient with the distant metastasis also one lymph node metastasis was analysed, and both were TERTp (c.1−146C > T) and NRAS (Q61R) mutated." (PMID 32659948, 2020). "A second patient harbored an NRAS mutation in a lymph node metastasis, while the matching brain metastasis was NRAS wild type." (PMID 32913556, 2020). "Associations between PIK3CA or NRAS mutations and patient characteristics, such as age, gender, tumor location, histological type, tumor differentiation, invasion depth, lymph node metastasis, distant metastasis or TNM stage, were statistically insignificant." (PMID 26691448, 2015). "In this study, we found a significant association between lymph node metastasis and NRAS mutation." (PMID 34110110, 2022). "NRAS mutation was highly correlated with lymph node metastasis (p = .000)." (PMID 34110110, 2022). "The existence of the NRAS mutation is significantly correlated with lymph node metastasis." (PMID 34110110, 2022). "Its potential in predicting lymph node metastasis, as well as gene mutations such as KRAS, NRAS, and BRAF has been evaluated." (PMID 41295561, 2025). "Furin was significantly increased in carcinomas with lymph node metastasis (p = 0.037) and with wild-type NRAS status (p = 0.028) (respectively)." (PMID 37568724, 2023). "Given the median number of mt/Mb, TMB-high lymph node metastases showed a higher frequency of ATM (13.3% vs 2.6%, p = 0.003) and NRAS (5.7% vs 0.9%, p = 0.04) mutations and more commonly manifested overexpression of PD-L1 (7.9% vs 0.9%, p = 0.014)." (PMID 34707195, 2021). "Significant associations were found between NRAS mutations and the absence of vascular invasion or lymph node metastases." (PMID 31456750, 2019). "Agreement coefficients for mutational concordance between primary and paired lymph node deposits were not calculated for NRAS mutations due to the small number of NRAS mutated cases and their corresponding lymph node metastasis." (PMID 28680105, 2017). "One case of PTC-FV harbored lymph node metastasis and was negative for the BRAF or NRAS mutation, while none of the PTMC-FV cases exhibited lymph node metastasis." (PMID 28680105, 2017).
angiosarcoma (15 papers, 2010 to 2025). A malignant tumor arising from the endothelial cells of the blood vessels. "Immunohistochemistry and gene testing confirmed the presence of angiosarcoma with lung metastases (stage IV, with NRAS mutation)." (PMID 40258747, 2025). "Ultimately, the patient was diagnosed with angiosarcoma derived from endothelial cells of vascular origin with multiple lung metastases (stage IV, with NRAS mutation)." (PMID 40258747, 2025). "Canine spontaneous hemangiosarcoma is a useful model for angiosarcoma both in their histologies and common driver mutations, including NRAS, PLCG1, PIK3CA, and TP5321." (PMID 36658200, 2023). "The other HRAS Q61L mutation and the NRAS G12D were both identified in (primary) idiopathic angiosarcomas, respectively." (PMID 34040639, 2021). "Moreover, in the Angiosarcoma Project NRAS was mutated in two breast ASs and one cutaneous AS, while HRAS was mutated in two ASs of the breast." (PMID 38137511, 2023). "We attribute the difference in the overall survival of PIK3CA and NRAS between dogs and humans to the high frequency of hemangiosarcoma analyzed in this study, representing 19% of studied dogs." (PMID 36658200, 2023). "In angiosarcomas, activating RAS mutations (HRAS and NRAS) were identified in three samples (16%)." (PMID 34040639, 2021). "Fitting previous studies of angiosarcomas, in 3 of 19 analyzed angiosarcomas (16%) activating RAS mutations [2 HRAS (Q61) and 1 NRAS (G12)] were identified." (PMID 34040639, 2021).
myeloproliferative neoplasm (14 papers, 2011 to 2026). A clonal hematopoietic stem cell disorder, characterized by proliferation in the bone marrow of one or more of the myeloid (i.e., granulocytic, erythroid, megakaryocytic, and mast cell) lineages. "A panel of NRAS mutations renders myeloproliferative neoplasms resistant to ruxolitinib, a JAK inhibitor." (PMID 41502952, 2025). "Oncogenic RAS pathway mutations, including NRAS, are associated with a myeloproliferative neoplasm-like phenotype and associated with transformation from CMML to acute leukemia." (PMID 39759649, 2024). "In a murine BM transplantation model carrying NRAS G12D, a myeloproliferative disease similar to chronic myelomonocytic leukemia (CMML) was induced after a prolonged latency period." (PMID 37841434, 2023). "In EZH2-mutated patients with myelodysplastic or myeloproliferative neoplasms, the most common co-mutations were in ASXL1 (100%), NRAS, RUNX1, and STAG2 (29% each)." (PMID 33845873, 2021). "After ruling out myelodysplastic and other myeloproliferative diseases the patient was finally diagnosed as aCML according to the WHO criteria with mutations in the TET2 gene, the NRAS gene and in the KRAS gene." (PMID 34840744, 2021). "The efficacy of MEK inhibitors on myeloid NRAS/KRAS mutated leukemic cells have been tested using two different mouse models: a Mx1-Cre, KrasLSL-G12D mice, which develop a fatal myeloproliferative neoplasm and mice transplanted with NRAS mutated AML cells (NrasG12D AML cells)." (PMID 29455651, 2018). "Juvenile myelomonocytic leukaemia (JMML) is an aggressive myeloproliferative neoplasm (MPN) characterized by driver Ras pathway mutations in 85% of cases, including known oncogenic KRAS and NRAS substitutions." (PMID 26854029, 2016). "In mice, knock-in of FLT3-ITD or FLT3-TKD, as well as NRAS p.G12D and KRAS p.G12D, induced a myeloproliferative neoplasm, and an AML phenotype was obtained by combination with other variants." (PMID 36499582, 2022).
sarcoma (14 papers, 2012 to 2025). A usually aggressive malignant neoplasm of the soft tissue or bone. "Analogous to what was observed in mouse sarcoma cells, asparagine depletion was shown to reduce the growth of human sarcoma cell lines, including the growth of the NRAS-mutated rhabdomyosarcoma cell line RD." (PMID 33499165, 2021). "In addition, we detected a mutation in AKT2 and NRAS in the sarcoma." (PMID 33707617, 2021). "The rat sarcoma (RAS) genes, including HRAS, KRAS, and NRAS, encode a family of proteins regulating cell growth, differentiation, and apoptosis." (PMID 24782938, 2014). "Advancements in genetic and molecular profiling allowed several abnormalities located in the phosphatidylinositol-4,5-bisphosphate 3 kinase catalytic subunit alpha (PIK3CA) and neuroblastoma RAS viral oncogene homolog (NRAS) pathways to be identified in canine sarcomas." (PMID 39195816, 2024). "This may point to the evolution of a high-grade sarcoma from a H3F3A-negative, but FGFR1-positive subclone with acquisition of additional mutations in AKT2 and NRAS during tumor progression." (PMID 33707617, 2021). "About 30% of all human cancers bear activating rat sarcoma (RAS) mutations; in particular, Kirsten rat sarcoma (KRAS) mutations are considerably more frequent than Harvey rat sarcoma virus oncogene (HRAS) and Neuroblastoma RAS Viral Oncogene Homolog (NRAS) mutations." (PMID 37298264, 2023).
prostate carcinoma (13 papers, 2012 to 2025). A carcinoma that arises from epithelial cells of the prostate gland. "Several microRNAs have been shown to act as tumor suppressors by targeting NRAS in various cancer types, including breast, lung, colorectal, and prostate cancers." (PMID 37083947, 2023). "Moreover, miR-145-5p regulates several critical oncogenes including MYC, BRAF, and NRAS, which are known promoters of prostate cancer cell proliferation and clonogenic potential when aberrantly activated." (PMID 38673886, 2024). "The NRAS gene is a well know oncogene in cancer that encodes for a GTP binding intracellular protein that interacts with the EGFR receptor and in 2018 has proposed as a possible biomarker for advanced prostate cancer." (PMID 34157951, 2021). "MiR-421 can inhibit prostate cancer progression by attenuating NRAS protein expression." (PMID 27556696, 2016). "Finally, Usp9x KD in ERG-positive prostate cancer cells (VCaP) reduced NRAS protein content." (PMID 28198367, 2017). "Seven genes (ATM, BCL2, ERN1, FOS, NRAS, PIK3R1, and SP1) were regulated in opposite directions in patients with HD and prostate cancer." (PMID 37298337, 2023). "miRNAs in prostate cancer, the GPCPD1 and NRAS gene, and the same combination of let-7b-5p and let-7i-5p were involved." (PMID 34157951, 2021). "Finally, the “prostate cancer” pathway also includes DEGsSD that are relatively specific to the (human) prostate (SRD5A2, KLK2, NKX3-1 and CREB3L4), proto-oncogenes (EGFR, PDGFRA, PDGFRB, NRAS) and druggable candidates (PIK3CD, CTNNB1, PIK3CG, CDKN1A)." (PMID 34768937, 2021). "The “prostate cancer” pathway also comprises genes that are relatively specific to the (human) prostate (CREB3L4, KLK2, NKX3-1 and SRD5A2), proto-oncogenes (EGFR, NRAS, PDGFRA and PDGFRB), and druggable candidates (CDKN1A, CTNNB1, EGFR, NRAS, PDGFRA, PDGFRB, PIK3CD and PIK3CG)." (PMID 34768937, 2021).